ENSG00000201407
Synonyms: LOC124900492
Gene: Small nucleolar RNA gene on chromosome X (24,133,186 to 24,133,317, forward strand). Ensembl gene ENSG00000201407.
Gene Ontology:
Biological process: RNA processing
Cellular component: nucleolus
Homologues: Paralogues in human: SNORA68B (85% identical), SNORA68 (84% identical).